PLAC1 (placenta associated 1)
Description:
May play a role in placental development.
Synonyms: CT92; OOSP2L; OOSP2B
Tractability: Antibody: UniProt places it where antibodies can reach, with high confidence; UniProt predicts a signal peptide or a membrane-spanning region; its Gene Ontology location is reachable by antibodies, with medium confidence. PROTAC: ubiquitination databases record sites on it.
Gene: Protein-coding gene on chromosome X (134,565,837 to 134,764,355, reverse strand). Ensembl gene ENSG00000170965.
Subcellular location: Secreted
Subcellular location (Human Protein Atlas): Vesicles; Cytosol; Predicted to be secreted
Gene Ontology:
Biological process: placenta development
Cellular component: extracellular region
Homologues: Orthologues: chimpanzee PLAC1 (99% identical), macaque PLAC1 (95% identical), dog PLAC1 (74% identical), pig PLAC1 (57% identical), rabbit PLAC1 (55% identical), rat Plac1 (50% identical), mouse Plac1 (49% identical). Paralogues in human: OOSP2 (21% identical), OOSP1 (18% identical).
Diseases named in the same sentence as PLAC1 in open-access papers:
PLAC1 is named in the same sentence as 64 diseases in open-access papers, as found by Europe PMC text mining. Sharing a sentence is not in itself a finding about the gene and the disease. The quoted sentences say what the papers report.
breast cancer (26 papers, 2011 to 2025). A primary or metastatic malignant neoplasm involving the breast. "Placental-specific protein 1 (PLAC1) is an X-linked trophoblast gene that is re-expressed in several malignancies, including breast cancer, and is therefore a potential biomarker to follow disease onset and progression." (PMID 29432428, 2018). "Our results uncover that patients whose tumors exhibit a high level of Plac1 are associated with high risk of axillary lymph node and distant metastasis, which is an independent prognostic factor in breast cancer." (PMID 29704427, 2018). "In contrast to its transcriptional repression in all other adult normal tissues, PLAC1 is frequently activated and highly expressed in a variety of human cancers, in particular breast cancer, where it associates with estrogen receptor α (ERα) positivity." (PMID 24304549, 2013). "Since overexpression of NCOA3 in breast cancer has been shown to be associated with clinical parameters, we were interested if high PLAC1 expression is associated with NCOA3 overexpression." (PMID 24304549, 2013). "In the present study, we wished to determine if circulating levels of cell-free PLAC1 protein could serve as a diagnostic biomarker for breast cancer." (PMID 29432428, 2018). "In tested breast cancer tissues, we found that patients with high Plac1 expression are associated with worse clinical outcomes, which indicates that level of Plac1 expression in breast cancer tissues may serve as a risk predictor for patients." (PMID 29704427, 2018). "Our findings suggest that Plac1 and its associated factors play important roles in breast cancer invasion and metastasis and may serve as an effective therapeutic target for treatment of this disease." (PMID 29704427, 2018). "Indeed, PLAC1 was reported to enhance the proliferation of cervical and nasopharyngeal cancer, and PLAC1 is associated here with poor prognosis and can promote invasion in breast cancer and nasopharyngeal carcinoma." (PMID 39594630, 2024). "The report shows that the overexpression of PLAC-1 promotes cell migration and invasion in vitro and in vivo in cell lines derived from breast cancer and promotes cellular proliferation by activating the AKT pathway." (PMID 36016136, 2022). "Previously, we reported that PLAC1 is linked to the PI3K/AKT pathway and is critical for motility, migration, and invasion of breast cancer cells." (PMID 32499871, 2020). "We have previously shown that cyclin D1 expression and AKT phosphorylation are markedly reduced in breast cancer cell lines after PLAC1 knockdown." (PMID 32499871, 2020). "We studied human choriocarcinoma and breast cancer cell lines to explore the localization and receptor-ligand interactions, as well as the downstream effects of PLAC1." (PMID 32499871, 2020). "Here we extended this function of PLAC1 to placental cells, suggesting the reactivation of a placental pathway in breast cancer." (PMID 32499871, 2020). "With malignant transformation, PLAC1 is frequently activated and highly expressed in various tumor types, especially in breast cancer and prostate cancer." (PMID 32499871, 2020). "PLAC1 is a suitable candidate for cancer immunotherapy, since it is overexpressed in more than 80% of breast cancers samples, while overexpression of Her2/neu, the target of Herceptin monoclonal antibody, is utmost 25%." (PMID 31952435, 2020). "In EO771 mammary carcinoma cells, knockdown of PLAC1 resulted in the reduced expression of several inflammatory and immune factors, including Cxcl1, Ccl5, Ly6a/Sca-1, Ly6c, and leukemia inhibitory factor." (PMID 32499871, 2020). "To investigate how Plac1 promotes breast cancer progression, we performed proteomic analysis of the complexes that were pulled down by the Plac1 antibody." (PMID 29704427, 2018). "Overexpression of Plac1 promoted invasion and metastasis of breast cancer cells in vitro and in vivo." (PMID 29704427, 2018).
breast cancer (continued). "In conclusion, the serum level of PLAC1 in breast cancer subjects with DCIS, HER2+, triple-negative and ER+/PR+ subtypes was a sensitive indicator of disease in 40–60 percent of subjects based on the mean+2 SD of levels in control subjects." (PMID 29432428, 2018). "qRT‐PCR and western blotting revealed different expression levels of Plac1 in breast cancer cells (MCF‐7, MDA‐MB‐231, BT‐474, MDA‐MB‐453, MDA‐MB‐468, HCC‐1937, SKBR3, and T47D)." (PMID 29704427, 2018). "(2007) found the level of p‐AKT downregulated by knockdown of Plac1 expression in breast cancer cell lines." (PMID 29704427, 2018). "This further demonstrates that Plac1 promotes invasion and metastasis of breast cancer cells through interaction with Furin." (PMID 29704427, 2018). "PLAC1 protein expression in biopsies and circulating PLAC1 mRNA have been previously detected in subjects with breast cancer, particularly in those with hormone receptor-positive disease." (PMID 29432428, 2018). "The goals of this study are to explore the function of Plac1 in regulating breast cancer invasion and metastasis using in vitro and in vivo experiments and clinical specimens." (PMID 29704427, 2018). "The current report provides clinical and experimental evidence to support the tumor‐promoting role of Plac1 in breast cancer." (PMID 29704427, 2018). "By gain‐ and loss‐of‐function assays, we show that depletion of Furin in Plac1‐overexpressing breast cancer cells attenuated the Plac1‐induced expression of NICD, HES1, MMP2, and MMP9 and tumor cell invasion and metastasis." (PMID 29704427, 2018). "Here, we report that Plac1 is an important oncogenic and prognostic factor, which physically interacts with Furin to drive breast cancer invasion and metastasis." (PMID 29704427, 2018). "The function of Plac1 in promoting breast cancer aggressiveness provides a new mechanism for explaining the poorly understood metastasis and poor survival of breast cancer patients with aberrant Plac1 overexpression." (PMID 29704427, 2018). "Sera from 117 preoperative/pretreatment breast cancer patients and 51 control subjects, including those with fibrocystic disease, were analyzed for the presence of PLAC1 protein as well as its expression by IHC in tumor biopsies in a subset of subjects." (PMID 29432428, 2018). "Recently, placenta-specific 1 (PLAC1)-specific HLA-A0201-restricted TCR-engineered CD8+ T cells were developed to kill breast cancer cells by producing IFN-γ and TNF-α." (PMID 29848327, 2018). "For example, a previous study using siRNA inhibition of Plac1 in breast cancer cell lines effectively suppressed tumor migration and invasion." (PMID 29704427, 2018). "Kaplan–Meier curve and multivariate analysis demonstrated that high Plac1 expression in breast cancer tissues was proven to be a significant and independent prognostic factor for MFS." (PMID 29704427, 2018). "Plac1 is reexpressed in several malignancies, and reduction of Plac1 in breast cancer cells inhibits proliferation and invasion." (PMID 28077942, 2016). "Due to its localization on the surface of cancer cells, PLAC1 provides accessibility to antibodies make them attractive candidates for targeted immunotherapeutic approaches for breast cancer and other tumor types." (PMID 24912876, 2014). "In one series of experiments with MCF7 breast cancer cells, RNAi-mediated silencing of PLAC1 succeeded in significantly reducing migration and invasion capabilities and almost completely ablating proliferation." (PMID 24757447, 2014). "We next assessed PLAC1 expression in matched tissues from breast cancer patients comparing expression in the tumor mass relative to adjacent non-tumor tissue." (PMID 24912876, 2014). "Knockdown of PLAC1 in breast cancer cells not only blocks cell cycle and proliferation, but also impairs cell motility, migration and invasion probably through inhibiting the cyclin D1 and the phosphorylation of AKT kinase." (PMID 24912876, 2014).
breast cancer (continued). "Several reports over the past few years have demonstrated PLAC1 expression in a variety of human solid tumors including lung cancers, breast cancers, hepatocellular and colorectal cancers, gastric cancers, and uterine cancers." (PMID 24757447, 2014). "The prominent expression and function of PLAC1 particularly in breast cancer led our attention to this co-activator family." (PMID 24304549, 2013). "Applying quantitative real-time RT-PCR (qRT-PCR), Western Blot analysis and chromatin immunoprecipitation, we analyzed the involvement of NCOA1, NCOA2, NCOA3 in the ERα-mediated transactivation of PLAC1 in the breast cancer cell lines MCF-7 and SK-BR-3." (PMID 24304549, 2013). "In this study, we have characterized the role of the p160/NCOA family of co-activators in the regulation of PLAC1 in breast cancer cells." (PMID 24304549, 2013). "Among the tumors where PLAC1 expression has been detected are nonsmall cell lung cancers, breast cancers, hepatocellular and colorectal cancers, and gastric cancers." (PMID 23935632, 2013). "In conclusion, our results shed further light on the composition of the E2/ERα-mediated transactivation complex at the PLAC1 promoter in breast cancer cells." (PMID 24304549, 2013). "In this study, we identified NCOA3 as a selective co-activator of ERα-mediated transactivation of PLAC1 in MCF-7 breast cancer cells." (PMID 24304549, 2013). "In recent years, evidence has accumulated that PLAC1 is also expressed in a variety of human solid tumors, notably in breast cancers." (PMID 23935632, 2013). "In a variety of human cancers, in particular breast cancer, PLAC1 is frequently activated and highly expressed." (PMID 24304549, 2013). "Indirect support for this idea comes from experiments in MCF-7 and BT-549 breast cancer cells showing that PLAC1 knockdown significantly reduces cell motility, proliferation, and invasiveness." (PMID 23935632, 2013). "Transcript expression of NCOA3 and PLAC1 in 48 human breast cancer samples was examined by qRT-PCR and statistical analysis was performed using Student’s t-test." (PMID 24304549, 2013). "PLAC1 (placenta-specific protein 1) is expressed in breast cancer and could be a serum biomarker for breast cancer." (PMID 35012580, 2022). "Moreover, NCOA3 is a selective co-activator of ERα-mediated transactivation of PLAC1, novel cancer-associated placental in MCF-7 breast cancer cells." (PMID 32212785, 2020). "PLAC1-fliC, as a cancer vaccine candidate, might be suitable and specific for breast cancer, which could evoke humoral and cellular immunity against this type of tumor." (PMID 31952435, 2020). "We demonstrate firsthand the potential role of PLAC1 in the tumorigenesis of breast cancer cells and choriocarcinoma cells via formation of a trimeric complex between PLAC1, FGF7, and FGFR2IIIb, which binds to HSGAGs in the ECM, and leads to cell proliferation via the activation of AKT." (PMID 32499871, 2020). "The aim of this study was to design a fusion protein construct, as an effective vaccine, consisting of PLAC1 (as a specific antigen) and Salmonella enterica fliC (as a bacterial adjuvant) that can stimulate humoral and cellular immune responses against breast cancer." (PMID 31952435, 2020). "In conclusion, our investigation regarding probable vaccine for breast cancer reveals that PLAC1-fliC contains suitable structure and stability that could effectively stimulate both cellular and humoral immunity and might be safe to administer." (PMID 31952435, 2020). "Therefore, PLAC1-fliC is a chimeric protein, which can be considered a suitable candidate against breast cancer." (PMID 31952435, 2020). "Additionally, similar effects of FGF7 stimulation on AKT phosphorylation following PLAC1 knockdown in breast cancer cell lines SkBr3 and T47D were shown." (PMID 32499871, 2020). "PLAC1 is a cancer/testis antigen, prevalent in breast cancer and rarely found in normal tissues." (PMID 31952435, 2020).
breast cancer (continued). "The use of serum PLAC1 as biomarker in breast cancer merits further study." (PMID 29432428, 2018). "To determine whether Plac1 may serve as a biomarker of early‐stage breast cancer, we performed Kaplan–Meier curve analysis on breast cancer patients with T1 and T2 stage disease." (PMID 29704427, 2018). "In estrogen-dependent breast cancer cells, PLAC1 expression was downregulated by antiestrogen treatment further suggesting that it may be a useful biomarker to follow treatment responsiveness and resistance in patients with hormone-dependent tumors." (PMID 29432428, 2018). "To test whether overexpression of Plac1 promotes the metastasis of breast cancer cells in vivo, we injected Plac1‐overexpressing MDA‐MB‐231 cells or control cells into tail veins of nude mice." (PMID 29704427, 2018). "Moreover, to investigate the prognostic value of Plac1 in patients with early‐stage breast cancer, 176 clinical stage T1 and T2 breast cancer cases were studied and revealed that Plac1 overexpression is correlated with worse OS and MFS." (PMID 29704427, 2018). "Nevertheless, the precise role of Plac1 in regulation of breast cancer metastasis and progression remains unclear." (PMID 29704427, 2018). "Those clinical and mechanistic data strongly demonstrate the important role of Plac1/Furin/NICD/PTEN signaling axis in breast cancer progression, which could serve as a potential target for metastatic breast cancer." (PMID 29704427, 2018). "As a step toward this goal, we conducted a pilot study to determine whether serum levels of Placental-specific protein 1 (PLAC1) could distinguish between different subtypes and stages of breast cancer." (PMID 29432428, 2018). "Notably, circulating PLAC1 mRNA levels covering a 5-log range were detected in the majority of subjects with primary breast cancer, and were greater in women with estrogen receptor positive (ER+) tumors." (PMID 29432428, 2018). "Because of the restrictive expression and immunogenicity of Plac1, using it as an immunotherapy target could improve the prognosis of patients with breast cancer." (PMID 29704427, 2018). "However, further experiments are required to also show a functional correlation between E2-induced breast cancer cell proliferation and PLAC1 expression." (PMID 24304549, 2013). "Silencing of NCOA3 results in loss of PLAC1 transactivation after E2-stimulation only in ERα-positive MCF-7 but not in ERα-negative SK-BR-3 breast cancer cells." (PMID 24304549, 2013). "Moreover, significant higher transcript levels of PLAC1 were found only in ERα-positive human breast cancer samples which also show a NCOA3 overexpression." (PMID 24304549, 2013). "The closest any cancer has come is 29 of 32 breast cancers (90.6%), while other tumors such as nonsmall cell lung cancer (5 of 8, 62.5%), hepatocellular cancer (32 of 69, 46.4%), and colorectal cancer (22 of 42, 52.4%) present PLAC1 expression much less often." (PMID 23935632, 2013). "In the present study, we examined the involvement of p160/NCOA family members in the regulation of PLAC1 in ERα-positive and -negative breast cancer cells and identified NCOA3 as a selective co-activator of ERα-mediated transactivation of PLAC1 in ERα-positive MCF-7 breast cancer cells." (PMID 24304549, 2013). "Thus our data introduce PLAC1 as a possible downstream effector of NCOA3 mediated actions in ERα-positive breast cancer cells." (PMID 24304549, 2013). "Noteworthy, silencing of NCOA3 in MCF-7 cells did not result in complete loss of PLAC1 expression, as basal expression of PLAC1 in breast cancer is not dependent on ERα-signaling but rather on the presence of SP1 and C/EBPβ-2." (PMID 24304549, 2013). "Additionally, C/EBPbeta2 is expressed in breast cancer cell lines and can transactivate cyclin D1 and PLAC1, two genes whose protein products are involved in proliferation and commonly upregulated in breast cancer." (PMID 21980398, 2011).